ERN2 (endoplasmic reticulum to nucleus signaling 2)
Description:
Induces translational repression through 28S ribosomal RNA cleavage in response to ER stress. Pro-apoptotic. Appears to play no role in the unfolded-protein response, unlike closely related proteins.
Synonyms: hIRE2p; IRE1b; IRE1-BETA; IRE2p
Tractability: Small molecule: a high-quality ligand is known; it belongs to a druggable protein family. Antibody: UniProt predicts a signal peptide or a membrane-spanning region. PROTAC: a small molecule that binds it is known.
Target class: Enzyme; Transferase
Gene: Protein-coding gene on chromosome 16 (23,690,292 to 23,713,255, reverse strand). Ensembl gene ENSG00000134398.
Subcellular location: Endoplasmic reticulum membrane
Subcellular location (Human Protein Atlas): Cytosol; Endoplasmic reticulum
Gene Ontology:
Molecular function: ATP binding; endonuclease activity; magnesium ion binding; protein serine kinase activity; protein serine/threonine kinase activity; protein kinase activity; RNA endonuclease activity; RNA nuclease activity
Biological process: apoptotic chromosome condensation; negative regulation of DNA-templated transcription; protein phosphorylation; rRNA catabolic process; intrinsic apoptotic signaling pathway in response to endoplasmic reticulum stress; IRE1-mediated unfolded protein response; response to endoplasmic reticulum stress; apoptotic process; endoplasmic reticulum unfolded protein response; mRNA processing; positive regulation of JNK cascade; regulation of DNA-templated transcription; RNA catabolic process
Cellular component: endoplasmic reticulum; endoplasmic reticulum membrane; IRE1-TRAF2-ASK1 complex; endoplasmic reticulum quality control compartment
Genetic constraint (gnomAD): Loss-of-function variants: 104 observed, 101.23 expected, observed/expected ratio (o/e) 1.03, 90% interval 0.88 to 1.21. The upper end of that interval is the gene's LOEUF score, 1.21, which puts it in group 5 of 6, group 1 being the genes least tolerant of losing a copy. Missense variants: 1,209 observed, 1,209.3 expected, observed/expected ratio (o/e) 1, 90% interval 0.95 to 1.05. Synonymous variants: 521 observed, 507.06 expected, observed/expected ratio (o/e) 1.03, 90% interval 0.95 to 1.11.
Homologues: Orthologues: chimpanzee ERN2 (99% identical), macaque ERN2 (90% identical), rabbit ERN2 (86% identical), pig ERN2 (86% identical), dog ERN2 (84% identical), guinea pig ERN2 (83% identical), mouse Ern2 (81% identical), rat Ern2 (81% identical), zebrafish ern1 (50% identical), Caenorhabditis elegans ire-1 (38% identical), Drosophila melanogaster Ire1 (38% identical). Paralogues in human: ERN1 (52% identical).
Diseases named in the same sentence as ERN2 in open-access papers:
ERN2 is named in the same sentence as 24 diseases in open-access papers, as found by Europe PMC text mining. Sharing a sentence is not in itself a finding about the gene and the disease. The quoted sentences say what the papers report.
colitis (17 papers, 2012 to 2024). Inflammation of the colon. "Consistent with previous studies, Ern2–/– mice were also more susceptible to DSS-associated colitis." (PMID 35727638, 2022). "Notably, recipients of the Ern2–/– microbiota had decreased expression of goblet cell marker genes (including Ern2) and increased susceptibility to DSS-associated colitis." (PMID 35727638, 2022). "The ERN2-deficient mice resemble, in many ways, the Winnie mouse model in which misfolded MUC2 induces ER stress, as indicated by elongated crypts, fewer mucus-filled goblet cells, and increased susceptibility to induced colitis." (PMID 36047499, 2022). "As could be expected by the weaker mucus protection in the ERN2-deficient animals, these mice were more susceptible to dextran sulfate sodium–induced (DSS-induced) colitis and Citrobacter infection." (PMID 36047499, 2022). "Mice lacking Ern2 had a dysbiotic microbial community that failed to induce goblet cell development and increased susceptibility to colitis when transferred into germ-free WT mice." (PMID 35727638, 2022). "Ern1 knockout (KO) in mice directly leads to death during the state of embryonic process, while Ern2 KO in mice results in increased ER stress, shortened latency of colitis, exacerbated DSS-induced colitis, induced idiopathic colitis, and aggravated severity of colitis." (PMID 35402506, 2022).
hyperlipidemia (3 papers, 2013 to 2018). "The upregulation of Ern2 may be beneficial in avoiding diet-induced hyperlipidaemia; therefore, the downregulation of hepatic Ern2 in IUGR foetuses may be associated with higher postnatal cholesterol levels, consistent with our previous report." (PMID 30524373, 2018).
inflammatory bowel disease (3 papers, 2020 to 2022). A spectrum of small and large bowel inflammatory diseases of unknown etiology. "As ERN2 is an important molecule enriched in these cells, understanding its role in general and in the goblet cell–specific ER function is important for developing therapeutic approaches for inflammatory bowel diseases, especially UC." (PMID 36047499, 2022).
ulcerative colitis (2 papers, 2021 to 2022). An inflammatory bowel disease involving the mucosal surface of the large intestine and rectum. "ERN2 association with ulcerative colitis and goblet cell development in primary human colonoids." (PMID 35727638, 2022). "To determine whether our findings were relevant to humans, we first analyzed gene expression for individuals with ulcerative colitis (UC), as molecular and histologic features of UC resemble the goblet cell, mucus layer, and microbial defects seen in Ern2–/– mice." (PMID 35727638, 2022).
adrenocortical tumors (1 paper, 2024). "In particular, ERN2, a UPR marker, was highly expressed in adrenal medullary tumor and PitNET datasets obtained by ACME HS and nuclei isolation methods, in adrenocortical tumors by enzymatic digestion, and in thyroid carcinomas by the ACME HS method." (PMID 39839668, 2024).
cholangiocarcinoma (1 paper, 2020). A carcinoma that arises from the intrahepatic biliary tree (intrahepatic cholangiocarcinoma) or from the junction, or adjacent to the junction, of the right and left hepatic ducts (hilar cholangiocarcinoma). "For example, ERN2 (Tbio) is the second-highest-scoring kinase in BRCA and cholangiocarcinoma (CHOL) and sixth in LIHC." (PMID 33205077, 2020).
lung adenocarcinoma (1 paper, 2021). A carcinoma that arises from the lung and is characterized by the presence of malignant glandular epithelial cells. "Recently, ERN2 was found differentially expressed in different mediastinal lymph node metastasis (MLNM) in lung adenocarcinoma." (PMID 33801837, 2021).
lung carcinoma (1 paper, 2022). "BDMC increases ER stress-associated proteins expression such as HSPA5, DDIT3, ERN1, ERN2/IRE-1β, ATF6, ATF6B and CASP4, which results in cell apoptosis in the human lung cancer NCI H460 cell line." (PMID 36497321, 2022).
MODY (1 paper, 2023). "Similarly, in the case of MODY diabetes, the heterozygous MLKL loss-of-function mutation also segregated with heterozygous deleterious mutations in the known MODY gene PDX1, as well as ERN2, NIPAL4 and SPTBN4 in affected individuals." (PMID 36755069, 2023).
infection (6 papers, 2012 to 2023). The state of being infected such as from the introduction of a foreign agent such as serum, vaccine, antigenic substance or organism. "At 8 days after infection, Ern2–/– mice had approximately 10-fold higher levels of pathogen in stool." (PMID 35727638, 2022). "After peak levels of infection were attained (e.g., 13 days after infection), WT and Ern2–/– mice had similar degrees of tissue colonization and epithelial damage." (PMID 35727638, 2022). "Thus, ERN2 is required for proper assembly of the mucus barrier that protects the epithelium from infection and chemical injury." (PMID 35727638, 2022). "The mutants Ljsymrk, Ljnup85, Ljnup133 and Mtern1/ern2 double mutant are non-nodulating mutants that show increased and non-effective—“spatula like”, swelling and branching—RH deformation, and no infection chambers or IT development." (PMID 36986997, 2023).
cancer (5 papers, 2020 to 2025). A tumor composed of atypical neoplastic, often pleomorphic cells that invade other tissues. "However, our analysis suggests that ERN2 can be explored as a potential target in multiple cancer types despite limited literature support." (PMID 33801837, 2021). "For the first time, we were able to detect the expression of IRE1β (ERN2) mRNA in human MCL cell lines (HMC-1.1 and HMC-1.2), and other cancer cell lines." (PMID 38727283, 2024). "Among these, the genes PKMYT1, PNCK, BRSK2, ERN2, and STK31 were significant in survival in five or more cancers." (PMID 33801837, 2021). "Other less understudied commonly upregulated kinases that were frequently found to be significant in survival (≥5 cancers) included the BRSK2, ERN2, PNCK, and STK31 kinases." (PMID 33801837, 2021). "Because of its understudied nature, there are little to no cancer-related publications available to assess the literature evidence of ERN2 as a potential target." (PMID 33205077, 2020).
ERN2 also shares sentences with these, for which no sentence is quoted: asthma (2 papers); colorectal cancer (2); pancreatic ductal adenocarcinoma (2); tumor (2); viral infection (2); colon carcinoma (1); dyslipidemia (1); fatty liver (1); ileitis (1); intestinal inflammation (1); melanoma (1); pancreatic cancer (1); thyroid carcinomas (1).